BNIP3 (BCL2 interacting protein 3)
Diseases named in the same sentence as BNIP3 in open-access papers (continued):
Sharing a sentence is not in itself a finding about the gene and the disease.
Sepsis (11 papers, 2012 to 2025). Sepsis is defined as life-threatening organ dysfunction caused by a dysregulated host response to infection. "Sepsis‐induced ARDS hypoxic conditions upregulates the transcription of Bcl‐2 interacting protein 3 (BNIP3) by the induction through Hypoxia‐inducing factor 1 (Hif1)." (PMID 36169246, 2022). "Taken together, these studies support our finding that both Bnip3 and Naif1 are involved in EC death and permeability in sepsis." (PMID 34638535, 2021). "Lc3b and Bnip3 increased in the TA after 24, 48, and 96 h of sepsis, while Sqstm1 and Foxo1 increased after 24 and 48 h." (PMID 31660704, 2019). "Sepsis‐induced increases in Lc3b, Sqstm1, Bnip3, and Foxo1 mRNA levels were relatively higher in the TA than in the DIA." (PMID 31660704, 2019). "BNIP3 signaling stimulates pathological responses under conditions of hypoxia and ischemia/reperfusion, however, whether BNIP3 is pathological in sepsis-induced cardiac dysfunction and how Beclin-1 interacts with BNIP3 require further investigation." (PMID 30744190, 2019). "Sepsis survivors exhibited increased levels of PARKIN, PINK1 and BNIP3, suggesting impairment in both ubiquitin‐dependent and receptor‐mediated mitophagy pathways, but this was not thoroughly investigated." (PMID 40817441, 2025). "Sepsis increased the protein expression of PINK1, Ser65 phospho PARKIN, full‐length PARKIN and BNIP3 in survivors, suggesting that mitophagy signalling pathways were activated in response to mitochondrial damage." (PMID 40817441, 2025). "In sepsis‐induced myocardial dysfunction, phlorizin, a new caloric restriction mimetic, activates autophagy and protects cardiomyocytes through the HIF‐1α/BNIP3 axis." (PMID 39611400, 2024). "Regarding the mitophagy pathway, the mRNA expression of Bnip3 increased 3.4-fold in the SPF group compared with the SF group (p < 0.05), and was lower in the Sepsis group than in the SPF group (p < 0.05)." (PMID 37106730, 2023). "During sepsis, LPS-induced HIF-1α expression upregulates the production of ROS, inflammatory cytokines, and proapoptotic proteins (e.g., caspase-3, BNIP-3, and Beclin-1), contributing to inflammation and apoptosis." (PMID 33567713, 2021). "However, the Sepsis mice did not generate such cytoprotective pathways (i.e., PGC1α or BNIP3 increases), likely contributing to their mitochondrial dysfunction and loss of mitohormesis." (PMID 37106730, 2023). "While the energy debt increased Bnip3 3.4-fold in the SPF mice, the Sepsis animals did not attain this level, suggesting an impairment in the PINK1-Parkin-independent mitophagy." (PMID 37106730, 2023).
ovarian carcinoma (10 papers, 2020 to 2025). A malignant neoplasm originating from the surface ovarian epithelium. "Higher levels of BNIP3 in samples isolated from ovarian cancer patients (treated with carboplatin together with doxorubicin or taxol) were associated with reduced survival, suggesting a role for BNIP3 in platinum-related resistance mechanism." (PMID 35459212, 2022). "Specifically, levels of the mitophagy receptor BNIP3 are higher both in resistant cells and in ovarian cancer patient samples resistant to platinum-based treatments." (PMID 35459212, 2022). "To further understand the contribution of BNIP3 in platinum-related mitochondrial autophagy, we also performed immunohistochemistry experiments in other samples of ovarian cancer patients (either sensitive or resistant)." (PMID 35459212, 2022). "We searched the online databases Gene Expression Omnibus and The Cancer Genome Atlas to analyze the correlation between BNIP3 level and overall survival and progression‐free survival in patients with ovarian cancer." (PMID 32412667, 2020). "In ovarian cancer, BNIP3 was reported to influence the proliferation and migration of ovarian cancer cells." (PMID 32412667, 2020). "In this study, BNIP3 silencing in A2780 and OVCAR4 cells led to a significant decrease in sensitivity to cisplatin, which suggested that cisplatin cytotoxicity was dependent on BNIP3 level in ovarian cancer cells." (PMID 32412667, 2020). "According to our results, cisplatin‐induced apoptosis is dependent on BNIP3 level, and the depletion of BNIP3 remarkably alleviates the cytotoxic effect of cisplatin in ovarian cancer cells." (PMID 32412667, 2020). "In this study, we examined the role of BNIP3 in ovarian cancer during cisplatin treatment and its correlation with clinical outcomes." (PMID 32412667, 2020). "Cisplatin‐induced BNIP3 up‐regulation in both protein and mRNA levels was observed in ovarian cancer lines." (PMID 32412667, 2020). "We first measured cisplatin cytotoxicity and BNIP3 levels before and after cisplatin exposure for ovarian cancer cell lines A2780, SKOV3, OVCAR4, OV2008, ES2 and HO8910." (PMID 32412667, 2020). "BNIP3 is up‐regulated by cisplatin in ovarian cancer cells and contributes to cisplatin‐induced cellular apoptosis in a caspase‐dependent manner." (PMID 32412667, 2020). "When evaluating the basic level of BNIP3 in ovarian cancer cells, we identified BNIP3 expression in all selected ovarian cancer cell lines." (PMID 32412667, 2020). "Taken together, our results indicate that cisplatin‐induced apoptosis was dependent on BNIP3 level in ovarian cancer cell lines." (PMID 32412667, 2020). "The mitochondrial autophagy-associated PINK1/parkin pathway, BNIP3 molecules, and mitochondrial Ca2+ absorption promotion in the MAM might all be used to manipulate ovarian cancer cell metastasis and drug resistance." (PMID 38711526, 2024). "In parallel, we measured BNIP3 expression in ovarian cancer patient samples." (PMID 35459212, 2022). "To investigate whether BNIP3 level is correlated with cellular cisplatin cytotoxicity, we knocked down BNIP3 expression in relatively platinum‐sensitive ovarian cancer cell lines to determine whether any concurrent cisplatin sensitivity variation occurs." (PMID 32412667, 2020). "High BNIP3 level remained correlated with poor OS in patients with serous (OS: 95% CI; HR = 1.23, 1.05–1.43; P = 0.0085) and advanced stage (OS: 95% CI; HR = 1.23, 1.06–1.43; P = 0.0058) ovarian cancer." (PMID 32412667, 2020). "However, considering the results of individual study and stratification analysis, the predictive value of BNIP3 in ovarian cancer should be interpreted delicately." (PMID 32412667, 2020). "Separate analysis of correlation between BNIP3 level and OS in patients with ovarian cancer." (PMID 32412667, 2020). "Therefore, in this study, we aim to evaluate the function of BNIP3 in ovarian cancer during cisplatin treatment and its correlation with clinical outcomes." (PMID 32412667, 2020).
ovarian carcinoma (continued). "Because BNIP3 correlated with cisplatin cytotoxicity in ovarian cancer cells, we hypothesized that cisplatin‐induced cellular apoptosis was to some extent dependent on BNIP3 level." (PMID 32412667, 2020). "Because BNIP3 level was significantly related to cisplatin‐induced apoptosis, we wondered whether BNIP3 could act as a biomarker for clinical outcomes in patients with ovarian cancer." (PMID 32412667, 2020). "Thus, BNIP3 is hypothesized to be an important target in ovarian cancer metastasis." (PMID 38711526, 2024). "We performed the analyses to examine the correlation between BNIP3 level and clinical outcomes such as OS and PFS in patients with ovarian cancer using online datasets." (PMID 32412667, 2020). "Correlation of BNIP3 level to OS and PFS in patients with ovarian cancer with varied clinical characteristics." (PMID 32412667, 2020). "Apoptosis and necrosis of ovarian cancer cell lines A2780 and OVCAR4 in reaction to cisplatin after BNIP3 regulation." (PMID 32412667, 2020). "Experimental studies have shown that expressions of BNIP3 and LC3-II, and mitochondrial autophagic activity, are significantly increased in ovarian cancer HO-8910PM cells under hypoxic conditions, thus initiating mitochondrial autophagy to maintain cell migration and invasion." (PMID 38711526, 2024). "Separate analysis of correlation between BNIP3 level and PFS in patients with ovarian cancer." (PMID 32412667, 2020). "However, the effect of BNIP3 regarding cell death in reaction to cisplatin in ovarian cancer is not clear." (PMID 32412667, 2020). "In addition, the truncated form of BNIP3 lacking the transmembrane domain abolished the mitochondria‐dependent cellular apoptosis induced by BNIP3 in ovarian cancer cells." (PMID 32412667, 2020). "However, the involvement of BNIP3 in cisplatin‐induced apoptosis in ovarian cancer is not clear." (PMID 32412667, 2020).
Stroke (10 papers, 2017 to 2024). Sudden impairment of blood flow to a part of the brain due to occlusion or rupture of an artery to the brain. "Using an adapted Rice-Vanucci model of neonatal stroke or hypoxia-ischemia encephalopathy (HIE), the investigators observed that pups deficient of BNIP3 had a decrease in mitophagy that resulted in significantly smaller infarct sizes in response to neonatal stroke and 7 days of reperfusion." (PMID 28401475, 2018). "To date, the role of BNIP3 in the central nervous system has mostly been investigated in the context of stroke and malignant glioblastoma multiforme." (PMID 38030595, 2024). "The roles of NIX and Bnip3 in mitophagy during stroke have challenged their conceptions of them as pro-apoptotic proteins; this also raises the question of how NIX and Bnip3 can be both neuroprotective and detrimental in stroke." (PMID 30501621, 2018). "Although both FUNDC-1 and Bnip-3 are involved in mitophagy induction, FUNDC-1 does not appear to influence neuronal mitophagy as extensively as Bnip-3, which contributes to the sequestration of mitochondria into autophagosomes, thereby triggering delayed neuronal death in stroke." (PMID 39594471, 2024). "Significant increases in the thick myelinated axon (G-ratio < 0.8) and decreases in the demyelinated axon (0.8 < G-ratio < 1) were observed in BNIP3 KO mice, suggesting that BNIP3 KO may maintain axonal myelination after preconditioning and stroke." (PMID 36551300, 2022). "Therefore, Bnip3 is a promising target for the control of cell survival or death by regulating mitophagy after stroke." (PMID 30501621, 2018). "Research has confirmed that in stroke models, BNIP3 and NIX interact, and downregulating BNIP3 leads to weakened mitochondrial autophagy, while NIX activation shows similar changes." (PMID 38650626, 2024). "A very insightful study has demonstrated the interaction between Bnip3 and NIX in stroke, with Bnip3 gene-silencing leading to a decrease of mitophagy and a neuroprotective effect in response to both of the vivo and vitro stroke models." (PMID 30501621, 2018). "In addition to the canonical mitophagy pathway, under hypoxic conditions induced by stroke, the reduction of hydroxylated hypoxia-inducible factor (HIF) accelerates HIF accumulation, enhancing mitophagy sensitivity by activating FUNDC-1, Bnip-3, and NIX." (PMID 39594471, 2024). "Bnip3 and NIX proteins integrate apoptosis and mitophagy signalling at different signalling domains, thus crosstalk between mitophagy and apoptosis may affect neuron cell death during stroke." (PMID 30501621, 2018). "The knockout of BNIP3 in mice can inhibit mitosis through the interaction of BNIP3 and LC3, with the manifestations of increased autophagy, decreased apoptosis and reduced cerebral infarction, indicating that the silencing of BNIP3 may be conducive to the neuroprotection after stroke." (PMID 36329694, 2022). "Although the study did not involve the Bnip3 expression in brain cells, it suggests that improving the tolerance of hypoxia by regulating Bnip3 expression to reduce the ROS generalisation or DNA damage may also prove beneficial to organisms adapted to hypoxia stress after stroke." (PMID 30501621, 2018).
malignant glioma (9 papers, 2014 to 2025). A grade III or grade IV glioma arising from the central nervous system. "BCL2 interacting protein 3 (BNIP3) is essential for arsenic trioxide (As2O3)-induced autophagy in malignant glioma cells." (PMID 36851010, 2023). "Nuclear BNIP3 has been shown to acts as a transcriptional repressor to reduce apoptosis-inducing factor expression and increase resistance to apoptosis in human malignant gliomas (Burton, Eisenstat & Gibson, 2009)." (PMID 33981491, 2021). "Moreover, chemical agents, such as arsenic trioxide, induced autophagic cell death in malignant glioma cells by upregulating BNIP3." (PMID 25115395, 2014). "Arsenic trioxide induced autophagic cell death in malignant glioma cells by upregulating BNIP3." (PMID 25115395, 2014). "Interestingly, BNIP3 plays a central role in As2O3-induced autophagic cell death in malignant glioma cells." (PMID 25232961, 2014).
neuroblastoma (9 papers, 2012 to 2025). Neuroblastoma (NB) is the most common solid, extracranial childhood tumor. "Since HIF1α is a transcription factor, we next asked if peroxides play indispensable role in HIF-dependent transcription by examining Eno2 and Bnip3 mRNA expression levels, which are two established HIF1α target genes, in neuroblastoma SH-SY5Y cells." (PMID 34596045, 2021). "In contrast, BNIP3-mediated mitophagy was also shown to protect neuroblastoma SH-SY5Y cells against TNF-α-induced death." (PMID 33879840, 2021). "In neuroblastoma, this group demonstrated that inhibition of TRPM2 triggers cell death and is associated with a decrease in HIF-1/2 and its downstream target BNIP3, leading to the accumulation of Hsp60 and Tom20 proteins, two key indicators of decreased autophagy and mitophagy." (PMID 37576339, 2023). "Taken together, accelerated neuroblastoma cell loss following exposure to autoantibodies in diabetes, TBI and TBI plus DM from patients having co-morbid Parkinson’s disease, or dementia may be mediated by neuroapoptosis involving (in part) increased Casp3, Bnip3 and Nae1 gene expression." (PMID 34013450, 2021). "In neuroblastoma cells, Miller’s group showed that inhibition or silencing of TRPM2 decreased hypoxia-inducible factor-1/2 (HIF)-1/2 and its downstream mitochondrial membrane proteins involved in mitophagy (BNIP3), ROS-scavenging (SOD1/2), and ATP synthesis (ETC., complexes)." (PMID 37576339, 2023).
Parkinson disease (9 papers, 2021 to 2025). A progressive degenerative disorder of the central nervous system characterized by loss of dopamine producing neurons in the substantia nigra and the presence of Lewy bodies in the substantia nigra and locus coeruleus. "Overexpression of BNIP3 improved ATP production in Parkinson's disease 105, and BNIP3/BNIP3L-mediated mitophagy protected against brain ischemic injury 106,107." (PMID 39247814, 2024). "This function may be one of the mechanisms responsible for MnCl2-induced neurotoxicity, suggesting that targeting BNIP3 is a potential strategy for the treatment of manganism and parkinsonism." (PMID 34078255, 2021). "It provides a focused analysis of the specific functions and activation mechanisms of key receptors—including BNIP3, NIX, FUNDC1, and AMBRA1—in models of Alzheimer’s disease, Parkinson’s disease, and amyotrophic lateral sclerosis." (PMID 41341510, 2025).
renal fibrosis (9 papers, 2019 to 2025). A final common manifestation of a wide variety of chronic kidney diseases characterized by glomerulosclerosis and tubulointerstitial fibrosis. "Severe renal fibrosis following UUO caused by BNIP3 deficiency could also be partially mitigated by mitochondria-targeted antioxidants." (PMID 36928344, 2023). "In line with our findings, a study demonstrated that HIF1α-BNIP3-mediated mitophagy possessed the ability to prevent from renal fibrosis by alleviating ROS production." (PMID 38789630, 2024). "In renal interstitial fibrosis, Bnip3 has been posited to activate autophagy and renal fibrosis as an effector of the HIF pathway in a mouse model of unilateral ureteral obstruction." (PMID 39056733, 2024). "BNIP3 deficiency increased the production of mitochondrial ROS, the NLRP3 inflammasome, and αSMA and TGFβ1 expression, indicating the protective role of BNIP3-mediated mitophagy in renal fibrosis." (PMID 36928344, 2023). "In this study, we showed that the tubular HIF1α-BNIP3 signaling pathway is involved in mitophagy and plays a protective role in renal fibrosis." (PMID 36928344, 2023). "This study aimed to explore the role of the HIF1α-BNIP3 pathway in mitophagy and the regulation of NLRP3 in renal fibrosis in UUO models by using BNIP3-knockout mice or NLRP3 inflammasome inhibitors." (PMID 36928344, 2023). "In the present study, we confirmed that the tubular HIF1α-BNIP3 signaling pathway is involved in mitophagy and protects against renal fibrosis." (PMID 36928344, 2023). "It has been documented that HIF-1α-BNIP3-mediated mitophagy mitigates renal fibrosis by inhibiting the activation of the NLRP3 inflammasome, and BNIP3-mediated mitophagy also exerts a protective effect on neuroinflammation by suppressing the assembly of the NLRP3 inflammasome." (PMID 40242759, 2025). "In this study, we showed that VDR could ameliorate renal fibrosis in STZ-induced diabetic mice by up-regulating the expression of BNIP3 and PINK1." (PMID 38697845, 2024). "(2023) they observed a significant increase in the expression levels of BNIP3 and HIF-1 α in UUO mice and a hypoxia-induced HK-2 cell model, as well as a significant up-regulation of TGF-β1 and α-SMA associated with renal fibrosis, accompanied by the activation of the NLRP3 inflammasome." (PMID 38680884, 2024). "Additionally, BNIP3 knockdown negated the benefits of activated mitophagy, and mitigated EndMT and renal fibrosis induced by Rictor knockout." (PMID 38769658, 2024). "In this study, we explored the regulatory role of HIF1α-BNIP3-mediated mitophagy in renal fibrosis." (PMID 36928344, 2023). "Furthermore, the function of HIF1α-BNIP3-mediated mitophagy and the downstream molecules in renal fibrosis also need to be explored." (PMID 36928344, 2023). "Furthermore, renal fibrosis was attenuated by MitoTEMPO and MCC950, indicating that HIF1α-BNIP3-mediated mitophagy protected against renal fibrosis by regulating the NLRP3 inflammasome." (PMID 36928344, 2023). "The protective effect of TSPs on renal fibrosis in DN partly depends on the regulation of mitophagy via Bnip3/Nix signaling to improve mitochondrial dysfunction, including mitochondrial fragmentation, the decreased MMP and over-production of mitochondrial superoxide and cellular ROS." (PMID 32679664, 2020). "Therefore, a therapeutic strategy by targeting HIF-1 α and BNIP3-mediated mitophagy could alleviate renal fibrosis and delay the progression of CKD." (PMID 38680884, 2024). "To date, the actual role of BNIP3-mediated mitophagy in renal fibrosis remains unknown." (PMID 36928344, 2023). "Thus, therapeutic strategies targeting HIF1α- and BNIP3-mediated mitophagy may alleviate renal fibrosis and delay the progression of CKD." (PMID 36928344, 2023). "In our study, there was more severe renal fibrosis, higher levels of mitochondrial ROS, and increased production of the NLRP3 inflammasome in BNIP3-KO mice following UUO." (PMID 36928344, 2023).